POSTN (periostin)
Diseases named in the same sentence as POSTN in open-access papers (continued):
Sharing a sentence is not in itself a finding about the gene and the disease.
scleroderma (continued). "Thus, periostin appears, at least in part, to directly increase Col1α1 expression in murine scleroderma via the αv integrin-mediated PI3K/Akt pathway." (PMID 22911870, 2012). "PN−/− mice were used to examine the contribution of periostin in the pathogenesis of scleroderma." (PMID 22911870, 2012). "Thus, our observations and those of others collectively indicate that periostin is involved in the multiple steps of skin fibrosis and is an attractive target for the treatment of scleroderma." (PMID 22911870, 2012). "Moreover, the expression of POSTN is upregulated in the lesional skin of scleroderma patients." (PMID 30186543, 2018). "Periostin may represent a potential therapeutic target for human scleroderma." (PMID 22911870, 2012). "Additionally, according to recent evidence, periostin may also contribute to scleroderma via the regulation of the Notch1 signaling pathway, another important pathway in skin sclerosis." (PMID 22911870, 2012). "In a skin tissue dataset, a fibroblast cluster expressing POSTN, ADAM12, and NREP was found to be higher in scleroderma than normal skin tissue samples." (PMID 40232153, 2025). "Mesenchymal fibroblast markers POSTN, ADAM12, COMP, and NREP were extensively expressed in scleroderma cluster 7 fibroblasts." (PMID 34140509, 2021). "The present study is the first to show that periostin is one of these pivotal matricellular proteins that accelerates pathologic fibrosis in both BLM-induced skin sclerosis and human scleroderma." (PMID 22911870, 2012). "However, it is still unknown whether periostin is involved in scleroderma." (PMID 22911870, 2012). "This phenomenon may be of general significance, as the expression of the markers POSTN and COMP of mesenchymal fibroblasts has also been observed in scleroderma fibroblasts." (PMID 35990663, 2022). "In scleroderma, the vitamin D analogue inhibits TGF β-induced POSTN expression to reduce fibrosis." (PMID 30400797, 2018). "Thus, while periostin is known to regulate collagen assembly, these data suggest that periostin in BLM-induced scleroderma is critical for excessive collagen synthesis." (PMID 22911870, 2012).
diabetes (14 papers, 2014 to 2025). "Periostin-deficient mice were protected from diabetes-induced cardiac dysfunction and myocardial damage, while overexpression of periostin held the opposite effects." (PMID 37993768, 2023). "Although hyperglycemia did not change the level of periostin in cardiomyocytes, global knockout of periostin can inhibit cardiomyocyte hypertrophy caused by diabetes." (PMID 37993768, 2023). "Thus, the underlying mechanism of periostin in the regulation of the metabolic pathway needs further exploration to clarify its clinical points against dyslipidemia, diabetes, and obesity." (PMID 27313402, 2016). "Likewise, loss of periostin suppressed diabetes-triggered upregulations of the pro-hypertrophic genes (ANP, BNP, β-MHC), pro-fibrogenic genes (Col I, Col III, α-SMA), pro-inflammtory genes (IL-1β, IL-6, TNF-α) and pro-oxidative genes (NOX2, NOX4, 12-LOX) at the mRNA levels." (PMID 37993768, 2023). "In this study, strong positive correlations were identified between periostin levels and key clinical parameters, including the diabetes duration (r = 0.795), BMI (r = 0.424), and HbA1C (r = 0.742)." (PMID 41316003, 2025). "Ishikawa reported high expression of periostin and tenascin-C in the trabecular meshwork of patients with diabetes." (PMID 39768583, 2024). "Deletion of periostin attenuated, while overexpression of periostin worsened diabetes-related cardiac dysfunction and injury." (PMID 37993768, 2023). "Noninvasive transthoracic echocardiography disclosed that ablation of periostin led to a significant improvement of diabetes-elicited cardiac diastolic and systolic dysfunction." (PMID 37993768, 2023). "Previous studies have also shown that periostin differentially expressed and upregulated contributes to the development and progression of various inflammatory diseases such as cancer, diabetes, and bowel disease." (PMID 35986791, 2022). "Taken all the results above together, our investigation demonstrates that periostin is a central element in diabetes related myocardium fibrosis, which is prevented by resveratrol via inhibition of ROS/ERK/TGF-β pathway." (PMID 26750922, 2016). "The purpose of this study is to examine the relations among plasma periostin, glucose and lipid metabolism, insulin resistance and inflammation in Chinese patients with obesity (OB), and type 2 diabetes mellitus (T2DM)." (PMID 27313402, 2016). "Next, we used transcriptomics on the molecular signaling pathways that may regulate the pathological cardiac dysfunction in diabetes induced by periostin." (PMID 37993768, 2023). "Consistent with the improvement of cardiac function, serum levels of lactate dehydrogenase (LDH) and creatine kinase-cardiac (CK-MB) were lower in periostin-deficient mice response to HFD and STZ, suggesting that periostin knockout mice were resistant to diabetes-induced heart damage." (PMID 37993768, 2023). "However, whether periostin mediates diabetes-induced cardiac damage and its role in the etiologies of DCM are unclear." (PMID 37993768, 2023). "Considering that periostin is well involved in liver TG metabolism, while inflammation is closely related to liver TG metabolism, obesity, and diabetes, we may speculate that the relations between periostin, inflammation, and metabolic disorders are quite strong." (PMID 27313402, 2016). "As expected, NAP1L2 downregulation rendered CF more invulnerable to HG-induced CF activation, as seen by lower fibrosis, oxidative stress, and inflammation, indicating that periostin is a positive regulator of NAP1L2, leading to CF activation in diabetes." (PMID 37993768, 2023). "The model included variables that were found to be associated with sclerostin based on prior bivariate analysis, including age, diabetes duration, eGFR, diastolic blood pressure, LDL-c, calcium, and periostin." (PMID 37919715, 2023).
diabetes (continued). "In contrast, diabetes, atrial fibrillation, admission NIHSS, periostin level, NLR, CRP as well as creatinine levels were inversely associated with ASPECT score < 6 calculated in univariate analysis." (PMID 36010292, 2022). "Indeed, at 50 ng/mL, an up-regulation was only observed for IFNγ in response to the diabetes and CAD marker IL-18, but a reduction for at least one of the three T-cell activity markers in response to all other biomarkers except CX3CL1 and periostin." (PMID 34281240, 2021). "Data from previous studies confirmed that renal periostin expression was strongly related to the progression of experimental hypertensive nephropathy and experimental model of CKD from 5/6 nephrectomy, ureteric obstruction and streptozotocin-induced diabetes." (PMID 25884625, 2015). "Although periostin overexpression itself did not exert any effect on body, nor did it affected global metabolic profiles, its ectopic expression induced cardiac dysfunction, and aggravated diabetes-evoked changes in echocardiographic indices." (PMID 37993768, 2023). "However, our study showed that comorbidities such as hypertension and diabetes mellitus did not affect periostin and NLR values." (PMID 34137680, 2021).
diabetic nephropathy (14 papers, 2015 to 2025). "and found that periostin deficiency attenuated kidney fibrosis in diabetic nephropathy by improving pancreatic β‐cell dysfunction and reducing kidney EMT." (PMID 39570100, 2024). "POSTN was also found to be associated with renal diseases, including diabetic kidney disease, immunoglobulin A nephropathy, and polycystic kidney disease." (PMID 35133974, 2022). "The aim of the present study was to investigate the determinants of urinary periostin and their associations with severe diseases of diabetic nephropathy." (PMID 25884625, 2015). "In addition, further studies are required to examine the pathogenic mechanisms of elevated periostin levels and their role in the early diagnosis of diabetic nephropathy." (PMID 25884625, 2015). "Urinary periostin is an associated renal derangement in patients with established diabetic nephropathy and it may be used as an early marker of diabetic renal injury." (PMID 25884625, 2015). "Studies have shown periostin mainly located in the dilated mesangium, tubulointerstitial and fibrotic regions of the diabetic kidney disease, which was negatively correlated with renal function." (PMID 39570100, 2024). "In humans, periostin is highly expressed in biopsies from patients with different renal diseases, including diabetic nephropathy." (PMID 35883655, 2022). "Periostin intraglomerular expression was weak and limited to focal fibrosis, an observation also made in human biopsies from patients with advanced diabetic nephropathy." (PMID 35883655, 2022). "A trend towards positive correlation between creatinine and serum periostin was found in adults with diabetic kidney disease." (PMID 34063373, 2021). "On the other hand, urinary periostin was negatively correlated with eGFR in adult patients with diabetic kidney disease and chronic allograft nephropathy." (PMID 34063373, 2021). "Periostin was revealed as a promising marker of diabetic kidney disease and chronic allograft nephropathy and increased periostin expression was found in patients with glomerulopathies." (PMID 34063373, 2021). "Nephroseq v5 webserver predicted the over expression of FN1, SPARC, LUM, VCAN, and POSTN with fold change of 2.808, 1.655, 6.25, 1.77, and 3.324 in diabetic nephropathy respectively." (PMID 34557161, 2021). "In some studies, periostin was shown to be upregulated in the renal tissues and in the urine of patients with diabetic nephropathy, as well as in mouse models of kidney injury." (PMID 32517742, 2020). "In urine periostin, ELISA demonstrated moderate to high sensitivity and specificity for diagnosing diabetic nephropathy." (PMID 25884625, 2015). "To evaluate the importance of periostin as a marker of kidney disease progression, we performed regression analyses with the hallmarks of diabetic nephropathy severity as dependent variables." (PMID 25884625, 2015). "A limitation of this research was the cross-sectional study design of increased urinary periostin with different stages of diabetic nephropathy." (PMID 25884625, 2015). "Immunohistochemical periostin expression was determined in kidney tissues from overt diabetic nephropathy." (PMID 25884625, 2015). "Further research should focus on a large population using a prospective cohort study for the role of urinary periostin in prognostic biomarkers to monitor the progression and therapeutic control of diabetic nephropathy." (PMID 25884625, 2015). "It was previously reported that periostin is highly expressed in patients with diabetic nephropathy as well in other human nephropathies, such as lupus, IgA nephropathy, autosomal dominant polycystic kidney disease, focal-segmental glomerulosclerosis, or membranous nephropathy." (PMID 35883655, 2022). "Our finding was supported by a recent study revealed that serum periostin and E‐cadherin might be regarded as dependable biomarkers in the pathogenesis of the early stage of diabetic nephropathy." (PMID 32597022, 2020).
diabetic nephropathy (continued). "Moreover, urinary periostin levels were increased significantly in diabetic patients with renal failure or albuminuria, suggesting a role of periostin in the progression of diabetic nephropathy." (PMID 28819200, 2017). "Our results identified periostin in urine of patients with the progression of diabetic nephropathy." (PMID 25884625, 2015). "However, no quantitative information exists on the relationship between urinary periostin and clinical staging of diabetic nephropathy." (PMID 25884625, 2015). "Therefore, immunohistochemical analysis confirmed that increased periostin expression in pathologic glomeruli and tubules was observed after established diagnosis of diabetic nephropathy." (PMID 25884625, 2015). "Therefore, urine periostin ELISA demonstrated moderate to high sensitivity and specificity for diagnosing diabetic nephropathy." (PMID 25884625, 2015). "In addition, significant differences were found between the urine periostin values in normoalbuminuric type 2 diabetes and other stages of diabetic nephropathy." (PMID 25884625, 2015). "Therefore, expression of periostin during different types of renal injury and among patients with type 2 diabetes, further suggests that periostin may serve as a quantitative marker of renal tubular loss linked to common pathogenic process in diabetic nephropathy." (PMID 25884625, 2015). "Moreover, the increase in urine periostin represents the severity of renal injury in patients with diabetic nephropathy." (PMID 25884625, 2015). "In addition, increased urine levels of periostin can be detected by enzymatic assay in kidney diseases that have been reported in a limited number of CKD patients including patients with diabetic nephropathy." (PMID 25884625, 2015). "Performance of urinary periostin in diagnosing diabetic nephropathy." (PMID 25884625, 2015). "However, previously, we could detect an increment in periostin expression by immunohistochemistry and immunoblotting method in early stages of experimental models of diabetic nephropathy." (PMID 25884625, 2015). "In the kidneys of patients with diabetic nephropathy, periostin is mainly expressed in the atrophied and non-atrophied tubule epithelial cells and the sclerotic glomerular mesangial area." (PMID 33241962, 2020). "Unfortunately, we did not demonstrate periostin expression in renal tissue from normoalbuminuria and microalbuminuria stages of diabetic nephropathy." (PMID 25884625, 2015). "Our study also confirmed that periostin staining was noted predominantly in atrophic and nonatrophic tubular epithelium, nodular sclerosis glomerulus with periglomerular and mesangial area in the setting of advanced diabetic nephropathy." (PMID 25884625, 2015). "When urine protein has not increased in the early stage of diabetic nephropathy, urine periostin has been significantly increased, which is also related to proteinuria and estimated glomerular filtration rate (eGFR), suggesting periostin may be an early and sensitive marker of renal injury." (PMID 33241962, 2020).
head and neck squamous cell carcinoma (14 papers, 2011 to 2024). A squamous cell carcinoma that arises from any of the following anatomic sites: lip and oral cavity, nasal cavity, paranasal sinuses, pharynx, larynx, and salivary glands. "Moreover, Jin and Yang (2019) showed that POSTN could be a promising potential diagnostic biomarker for head and neck squamous cell carcinoma." (PMID 35559040, 2022). "The serum periostin level in head and neck squamous cell carcinoma patients correlates well with that of VEGF-C and with malignant tumour behaviour, including increased tumour stage and lymph node metastasis." (PMID 34205668, 2021). "Specifically in oral leukoplakia and head and neck squamous cell carcinomas (HNSCCs), increased periostin expression appears to be directly proportional to the invasiveness and aggression of the disease." (PMID 34205668, 2021). "In head and neck squamous cell carcinoma (HNSCC), it was recently found that CAFs secretes periostin that significantly upregulates the CSCs-like phenotype, proliferation and invasion in HNSCC." (PMID 33898430, 2021). "We previously identified periostin as an invasion- and angiogenesis-promoting factor in head and neck squamous cell carcinoma (HNSCC)." (PMID 22952986, 2012). "In head and neck squamous cell carcinoma (HNSCC), increased POSTN expression was closely correlated with increased tumor angio- and lymphangiogenesis." (PMID 36077762, 2022). "POSTN is expressed more abundantly in invasive breast carcinoma, lung adenocarcinoma and squamous cell carcinoma, colon adenocarcinoma and head and neck squamous cell carcinoma (HNSCC)." (PMID 33114328, 2020). "Moreover, it was demonstrated that POSTN expression alone could induce lymphangiogenesis in head and neck squamous cell carcinoma (HNSCC) through the activation of intracellular Src and Akt." (PMID 36077762, 2022). "In addition, it was demonstrated that POSTN promoted the cancer stem cell (CSC)-like phenotype via the PTK7-Wnt/β-Catenin signaling pathway and enhanced proliferation and cell invasion in head and neck squamous cell carcinoma (HNSCC)." (PMID 36077762, 2022).
liver cancer (14 papers, 2007 to 2025). An epithelial or non-epithelial malignant neoplasm that arises from the liver. "This evidence strongly suggests POSTN is involved in the complex mechanisms that lead to liver cancer." (PMID 35676936, 2022). "Overall, the survival analysis based on the DEGs suggests that the expression of POSTN, HTRA3, LAYN, AFM and AANAT are associated with the outcomes of patients with liver cancer." (PMID 35676936, 2022). "This concept is in line with the over-expression of POSTN observed in a number of cancers (such as prostate, lung, pancreatic, breast and liver cancer), and the correlation established between POSTN expression in the primary tumor and a poor prognosis." (PMID 35567669, 2022). "Immunofluorescence staining of tissue samples obtained from cancer patients confirmed that POSTN (green) was co-expressed with CD133 (red) in liver cancer tissues with high POSTN expression." (PMID 34193219, 2021). "In liver cancer, average POSTN expression was also increased (902 ± 1308, n = 6) compared to normal tissue samples (14 ± 11, n = 5) (P = 0.16)." (PMID 18086302, 2007). "The only evidences for increased periostin expression in liver cancer reported so far come from immunohistochemical analysis of tumor tissues." (PMID 18086302, 2007). "Periostin (encoded by POSTN) is a matricellular protein that functions as critical factor in the development of hepatic inflammation, fibrosis, liver cirrhosis and liver cancer." (PMID 35676936, 2022). "Collectively, our results suggest the gut microbial metabolite TMAO and POSTN may represent potential therapeutic targets for liver cancer." (PMID 35676936, 2022). "Upregulation of POSTN, LAYN and HTRA3 and downregulation of AANAT and AFM were positively related to poorer overall survival in human liver cancer." (PMID 35676936, 2022). "Interestingly, higher expression of POSTN (OS HR = 1.63, 95% CI = 1.13–2.33, p = 0.0076; DSS HR = 1.8, 95% CI = 1.11–2.93, p = 0.016), LAYN (DSS HR = 1.61, 95% CI = 1.02–2.55, p = 0.039) and HTRA3 (OS HR = 1.53, 95% CI = 1.08–2.17, p = 0.015) were associated with poorer outcomes in liver cancer." (PMID 35676936, 2022). "Our previous research confirmed that Periostin (POSTN) is a crucial gene involved in the angiogenesis and pulmonary metastasis of HCC; it is highly expressed in 60% of liver cancer patients, and its high expression indicates poor prognosis." (PMID 34193219, 2021). "CSCs were shown to recruit TAMs at the tumor site through the release of soluble factors such as periostin (POSTN) in GBM and the activation of specific pathways such as the Hippo one in liver cancer models." (PMID 34572009, 2021). "Moreover, TMAO upregulates POSTN, NAPB, LAYN, and HTRA3 in liver cancer, and high expression levels of these genes are closely associated with suppression of the immune microenvironment and patient survival outcomes in liver cancer." (PMID 35676936, 2022).